RUNX1 (RUNX family transcription factor 1)
Diseases named in the same sentence as RUNX1 in open-access papers (continued):
Sharing a sentence is not in itself a finding about the gene and the disease.
Thrombocytopenia (continued). "Several genes responsible for Hermansky–Pudlak, Chediak–Higashi, and Griscelli syndromes have been sequenced, while in forms associated with thrombocytopenia, molecular abnormalities may involve transcription factors such as RUNX1 or FLI1." (PMID 32759727, 2020). "The degree of thrombocytopenia in individuals with RUNX1 mutations is typically mild to moderate and can vary widely even within affected families from individuals with a normal platelet count, to severe thrombocytopenia, to childhood MDS/AML at the time of first evaluation." (PMID 27248996, 2016). "Mutations in mouse and human Nfe2, Fli1 and Runx1 cause thrombocytopenia." (PMID 27457419, 2016). "Moreover, Runx1 deficiency in adult bone marrow attenuated megakaryocytic maturation and reduced blood platelet numbers (thrombocytopenia)." (PMID 23717578, 2013). "Based on findings from the previously reported patient and the current proband, it can be assumed that mosaic loss of RUNX1 may be sufficient to cause thrombocytopenia but only mild functional platelet defects (P6: slightly decreased LTA, no storage pool defect)." (PMID 41458504, 2025). "Furthermore, this study emphasizes the clinical vulnerability of individuals with germline RUNX1-FPDMM—as well as those with other thrombocytopenia-associated predispositions such as ETV6 or ANKRD26—and underscores the need for dedicated healthcare infrastructure." (PMID 41458504, 2025). "The increasing use of genetic testing in individuals with mild thrombocytopenia is expected to reveal a growing number of cases with germline RUNX1-FPDMM." (PMID 41458504, 2025). "Third, some patients had platelet function disorders in addition to δ-SPD, ie, thrombocytopenia and/or diminished luminoaggregometry in RUNX1 patients and an α-granule defect in Jacobsen syndrome." (PMID 41362696, 2025). "Mutations in the genes ANKRD26, RUNX1, and ETV6 cause three clinically overlapping thrombocytopenias characterized by a predisposition to hematological neoplasms." (PMID 39791724, 2024). "Germline RUNX1 mutations cause RUNX1 familial platelet disorder (RUNX1-FPD), which is characterized by thrombocytopenia, autoimmune diseases, and increased risk for MDS and AML, with an average age (in years) of onset in the mid-30s." (PMID 37581927, 2023). "Germline mutations in RUNX1 are causal for RUNX1 family platelet disorder (RUNX1-FPD) associated with a ~45% lifetime risk of malignancy, a varying degree of thrombocytopenia, and a high risk of eczema." (PMID 40225162, 2023). "Here, we observed somatic DNMT3A variants in four (11%) out of 37 RUNX1-FPD AMLs, one RUNX1-FPD myeloproliferative neoplasm, and one RUNX1-FPD thrombocytopenia patient." (PMID 35884491, 2022). "Patients with RUNX1-FPD often suffer from mild to moderate thrombocytopenia and/or platelet aggregation defects." (PMID 35884491, 2022). "MDS and AML are reported in about 40% of patients with RUNX1 germline mutations and in 8% of patients with ANKRD26 related thrombocytopenia, whereas 23% of the 73 patients with ETV6 familial thrombocytopenia described so far had hematological malignancies." (PMID 33802366, 2021). "The majority of ETV6/RUNX1-positive patients had combined moderate anemia and thrombocytopenia at the onset of disease, with a significantly higher proportion than the negative group (55 vs. 49.9%, P< 0.001; 75.0 vs. 70.9%, P= 0.007, respectively)." (PMID 34988026, 2021).
Thrombocytopenia (continued). "Mutations in transcriptional regulators, such as RUNX1 or ETV6, hit Mk maturation and perturb hematopoietic precursors leading to thrombocytopenia, impaired platelet function, and increased risk of clonal hematopoiesis." (PMID 32079152, 2020). "We recently reported that deleting the RUNX1C isoform in adult mice, whilst maintaining total RUNX1 expression, resulted in mild thrombocytopenia, due to impaired megakaryocytic specification but with normal megakaryocyte maturation." (PMID 29300724, 2018). "The ETV6 mutations, such as RUNX1 and ANKRD26 mutations, should be suspected among patients with thrombocytopenia with a family history of bleeding and/or hematologic malignances." (PMID 28955657, 2017). "As compared with previous reports, which described HSPC expansion, lymphopenia and thrombocytopenia in Runx1 conditional knockout mice,10, 11Runx1+/− mice display weaker hematopoietic phenotypes." (PMID 26745853, 2016). "Germline testing also revealed a heterozygous pathogenic splicing variant in RUNX1 (c.806-2A > G, r.Spl) in a patient with AML referred for transplantation for persistent thrombocytopenia following chemotherapy." (PMID 28007021, 2016). "Specific inactivation of Runx1 in maturating MK resulted in aberrant maturation and thrombocytopenia, as was also described by others upon abrogation of Runx1 activity in adult hematopoietic progenitor cells." (PMID 23717578, 2013). "Only one case is reported in the literature with a constitutional RUNX1 deletion leading to non-syndromic thrombocytopenia with MDS." (PMID 23025896, 2012). "Consequently, the RUNX1 deletion was missed, and her life-long thrombocytopenia and AML were inappropriately attributed to the germline GATA2 variants." (PMID 40148527, 2025). "As her husband lacked germline or somatic RUNX1 mutations and had no history of thrombocytopenia, a diagnosis of RUNX1-FPD or RUNX1-related CMML was not supported." (PMID 40919141, 2025). "It was suggested that the RUNX1/FLI1 complex negatively regulates ANKRD26 expression and that mutations in 5′-UTR of ANKRD26 disrupt RUNX1/FLI1 inhibition, which would lead to overexpression of ANKRD26 in megakaryocytes and defective proplatelet formation, and thus thrombocytopenia in patients." (PMID 40170493, 2025). "This is in line with previous findings reporting thrombocytopenia as the most common phenotypic feature seen in individuals with (likely) pathogenic germline RUNX1 variant and no HM." (PMID 35884491, 2022). "Among four patients with RUNX1-related thrombocytopenia, two patients (50%) had not abnormalities associated." (PMID 36507135, 2022). "The study using FPD/AML-iPSCs further revealed the differential effect of heterozygous RUNX1 mutation in mice vs. human, where no thrombocytopenia was observed in mice whereas it caused defects in in vitro generation of megakaryocytes in human iPSCs." (PMID 34685678, 2021). "RUNX1, ANKRD26, MYH9, ACTN1, and GP1BB had ranks of 1, 3, 8, 16, and 74, respectively, with none of the other loci in the top 20 ranks being known to be implicated in thrombocytopenia." (PMID 28669401, 2017). "Similar to RUNX1 and ANKRD26 mutation carriers, individuals with mutations in Ets variant 6 (ETV6)—associated with Thrombocytopenia 5—present with a variable degree of thrombocytopenia and mild-to-moderate bleeding tendencies." (PMID 27248996, 2016). "Importantly, the reduction in platelet count of Runx1+/− mice mimics the mild thrombocytopenia observed in FPD patients." (PMID 26745853, 2016). "So, in this patient the disruption of RUNX1 led to decreased expression and to thrombocytopenia." (PMID 23025896, 2012). "Hence, patients could have previously been diagnosed with RUNX1-related thrombocytopenia (RUNX1-RT or RUNX1-FPD, or FPD/AML, or FPDMM)." (PMID 40563486, 2025). "Additionally, mutations in ANKRD26, RUNX1, and ETV6 may predispose patients to thrombocytopenia by disrupting normal megakaryocyte function, significantly affecting platelet production." (PMID 40757104, 2025).
Thrombocytopenia (continued). "With the broader application of next-generation sequencing (NGS)-based gene panel analysis in individuals presenting with benign hematologic abnormalities such as thrombocytopenia, pathogenic RUNX1 variants were more frequently identified, independent of a hematologic malignancy." (PMID 41458504, 2025). "We previously established a murine model of MDS using patient-derived CBL exon 8/9 deletion (CBLΔE8/9) and RUNX1 S291 frameshift mutation (RUNX1S291fs) via BM transplantation (BMT), which showed phenotypically relevant characteristics of MDS-ineffective hematopoiesis including thrombocytopenia." (PMID 40813622, 2025). "cAMP enhances megakaryopoiesis through PKA-mediated activation of RUNX1 and GATA1, while its depletion in BDS likely exacerbates thrombocytopenia." (PMID 40332770, 2025). "Together, these differentiation defects recapitulated key characteristics of the preleukemic state found in RUNX1-FPD and MDS patients, namely thrombocytopenia, anemia, and neutropenia." (PMID 37581927, 2023). "Much of the current appreciation of the transcriptional control of thrombopoiesis rests on findings in knockout mice and in human pedigrees with syndromic thrombocytopenia, which point separately to three necessary TFs – NF-E2, FLI1 and RUNX1." (PMID 27457419, 2016). "Therefore, it is not surprising that RUNX1 haploinsufficiency due to constitutional chromosome deletions may cause a clinical phenotype which includes thrombocytopenia besides intellectual disability and other symptoms." (PMID 23025896, 2012). "Genetic testing has become an essential component of the diagnostic workup for thrombocytopenia and platelet function disorders and can reveal conditions such as RUNX1-FPDMM, which have significant implications for clinical management beyond thrombocytopenia and/or bleeding tendency." (PMID 41458504, 2025). "There was no impact of other laboratory (anemia, thrombocytopenia, serum tryptase) or genetic markers (mutations in SRSF2, ASXL1 or RUNX1) on OS." (PMID 37012462, 2023). "Initially, germline RUNX1 variants were classified as pathogenic if associated with FPD‐MM phenotype, but the discovery of new variants in cancer patients with no history of thrombocytopenia or familial haematological diseases is questioning this assertion." (PMID 36819173, 2023). "Other ITs to consider which may also present with thrombocytopenia with normal platelet size include RUNX1-related thrombocytopenia (RUNX1-RT), ETV6-related thrombocytopenia (ETV6-RT) and CYCS-related thrombocytopenia (CYCS-RT)." (PMID 35587581, 2022). "Another consequence is that the screening for a related donor for HSCT must be performed only by the analysis of RUNX1 which should not be restricted to members with thrombocytopenia." (PMID 27112265, 2016). "This phenotype was similar to the one observed in Runx1 conditional knockout mice, but no lymphocytopenia or thrombocytopenia was observed." (PMID 23344057, 2013). "A clonal anomaly in BM does not imply per se a diagnosis of MDS: a subgroup of BM hypoplastic disorders is directly due to chromosome structural anomalies with effects on specific genes, as was the case of RUNX1 and MPL in the patients here reported with diagnosis of SAA, thrombocytopenia, and CAMT." (PMID 23025896, 2012). "In thrombocytopenia and platelet function defect, the content of TLT-1 was reduced, recombinant soluble TLT-1 could potentiate fibrinogen binding to patient platelets, and TLT-1 was found to be positively regulated by RUNX1." (PMID 33964924, 2021). "Patients 1 and 2 reported here demonstrate that thrombocytopenia or BM hypoplasia with consequent SAA may in fact be due to structural anomalies of chromosome 21 involving RUNX1 which are not deletions, but complex rearrangements which may also be acquired instead of constitutional." (PMID 23025896, 2012).
Thrombocytopenia (continued). "In combination with the observed mild thrombocytopenia, it appears that the absence of RUNX1C may favor erythroid specification over megakaryopoiesis, a phenotype observed recently in mouse and human HSPCs depleted for total RUNX1." (PMID 26808730, 2016).
acute leukemia (54 papers, 2007 to 2026). A clonal (malignant) hematopoietic disorder with an acute onset, affecting the bone marrow and the peripheral blood. "In our clinical practice, we noted cases of AML with various RUNX1 lesions (beyond RUNX1::RUNX1T1 fusion and RUNX1 mutations) with aberrant expression of several B-cell markers, mimicking mixed-phenotype acute leukemia (MPAL)-B/myeloid at diagnosis." (PMID 40282530, 2025). "Chromosomal rearrangements involving RUNX1 or CBFβ, somatic point mutations in RUNX1 and amplification of RUNX1 have all been described in acute leukemia." (PMID 18671852, 2008). "Amongst acute leukemia patients in our cohort, one patient had RUNX1::RUNX1T1 translocation, while another had a biallelic CEBPA mutation, both of which are known to co-occur with CSF3R alterations." (PMID 40806796, 2025). "RUNX1 mutations were frequently observed in patients with EMS, and all patients with RUNX1 mutation presented with acute leukemia." (PMID 36930401, 2023). "CBFA2T3 and RUNX1 genes are also RUNX1 targets in myeloid cells and in mixed-phenotype acute leukemia." (PMID 33743795, 2021). "Genetic aberrations resulting in rearrangement of RUNX1, including generation of RUNX1 fusion genes, have been shown to be critical events in both myeloid and lymphoblastic acute leukemias." (PMID 29672642, 2018). "CASC15 expression was high in acute leukemia with RUNX1 translocations, and its expression in cells led to increased apoptosis and decreased engraftment in the hematopoietic system." (PMID 28724437, 2017). "LPXN was found to be a member of a fusion protein with RUNX1 in human acute leukemia where wild-type LPXN was shown to transform NIH 3T3 cells." (PMID 23349640, 2013). "For example, miR-17 upregulation, frequent in MLL-rearranged acute leukemia, would reduce RUNX1 levels and result in decreased RUNX1-mediated miR-17 transcriptional repression." (PMID 23344057, 2013). "Runx1 transcription factor is a key regulator of early hematopoiesis and a frequent target of chromosomal translocations in acute leukemias." (PMID 17626615, 2007). "In acute leukemia, rearrangements such as submicroscopic deletions and inversions have been associated with known and novel fusions, including KMT2A (MLL), ETV6::RUNX1, CBFB::MYH11 and RUNX1::RUNX1T1." (PMID 35158889, 2022). "RUNX1 is one of the most common targets of chromosomal translocations in acute leukemia." (PMID 23344057, 2013). "RUNX1 (AML1) is a member of the RUNT family of transcription factors and together with its cofactor CBFB (core-binding factor, beta subunit) represents the most common mutational target in human acute leukemia." (PMID 23311859, 2013). "We report for the first time CNL transformation to acute leukemia of mixed phenotype (MPAL type) in the setting of a germline CSF3R-W791* truncation mutation located on the same allele as CSF3R-T618I, suggesting increased susceptibility for RUNX1-related clonal transformation." (PMID 35200567, 2022). "To investigate whether the fusion proteins target a common transcription factor network we performed motif enrichment analysis on their binding sites, using weight matrices of AML1/RUNX1, C/EBPA, the ETS factor SPI1, GATA and TAL1, all transcription factors reported to be mutated in acute leukemias." (PMID 28030795, 2017). "In module 3, the results indicated that RUNX1, ZBTB16, GATA2 and MEIS1 which involved in the myeloid cell differentiation and the pathogenesis of acute leukemia showed higher levels of expression in cells from the MDS across differentiation." (PMID 38632656, 2024). "Neither acquisition of a RUNX1 point mutation or CN-LOH at the CSF3R locus readily explain the mixed myeloid and lymphoid phenotype associated with transformation to acute leukemia." (PMID 35200567, 2022).
myeloid leukemia (50 papers, 1999 to 2026). A clonal proliferation of myeloid cells and their precursors in the bone marrow, peripheral blood, and spleen. "Germline heterozygous variants in RUNX1 lead to Familial Platelet Disorder with Myeloid Leukemia Predisposition (FPD/AML)." (PMID 40427601, 2025). "Aberrant expression of RUNX1 is known to cause myeloid leukemia and since the first report in 2010 a number of studies have shown somatic mutations in the cohesin complex as responsible for myeloid leukemia." (PMID 29389897, 2018). "Runx1 plays a critical role in haematopoiesis, and Runx1 translocations or other mutations occur frequently in myeloid leukaemias, and less commonly in other cancer types." (PMID 27919034, 2014). "RUNX1 is a transcription factor with frequent inactivating mutations in myeloid leukemia." (PMID 24454681, 2014). "Indeed, low dosage of RUNX1, resulting from haploinsufficient or dominant negative mutations, lead to the development of myeloid leukemia, whereas amplification of RUNX1 gene is more often observed in lymphoid leukemia, particularly pediatric ALL." (PMID 18671852, 2008). "Other known myeloid leukemia predisposition genes, including DDX41 (P = 3.68e−4, β = 0.115770) and RUNX1 (P = 3.99e−4, β = 0.176099), were identified at a lower significance level than seen for CHEK2 pLoF variants." (PMID 40335619, 2025). "NHR1, also referred to as TAFH, is a hub for interaction with several transcription regulators and is required for transforming ability of RUNX1/RUNX1T1 fusion in myeloid leukemia." (PMID 39478125, 2024). "FoxP3 expression maintenance is controlled by the conserved non-coding sequence 2 (CNS2), which binds both acute myeloid leukemia-1 (AML1)/Runx1 and FoxP3 in mature Tregs." (PMID 38509593, 2024). "Transcriptome analysis of both patient samples and K562 myeloid leukemia cells overexpressing RUNX1::ERG revealed consistent MYC repression by the fusion protein." (PMID 37002311, 2023). "Genes dysregulated by ASXL2 loss largely overlapped with those of RUNX1 and AML1-ETO and were associated with alterations in a number of genes previously shown to promote myeloid leukemias." (PMID 28516957, 2017). "Transgenic mice expressing mouse Runx1 under the control of the GATA1 hematopoietic regulatory domain (HRD) were generated to determine the role of Runx1 in the development myeloid leukemia in mice." (PMID 22461792, 2012). "Hhex expression, in combination with a mutant form of additional sex combs-like 1 (Asxl1) an epigenetic modulator often mutated in myeloid leukaemia, was also found to enhance Runx1-ETO and Flt3-ITD-driven myeloid leukaemia via upregulation of Myb and Etv5 in mice." (PMID 37398663, 2023). "RUNX1 is also known as AML1 (Acute Myeloid Leukemia gene 1) because mutations, in most cases translocations, in this gene are frequently observed in patients with lymphoblastic and myeloid leukemia." (PMID 34421907, 2021). "And the interaction of ITGB4 promoter with some transcription factors in other disease is also reported, such as KLF4 in glioma 21, RUNX1 in myeloid leukemia 22, ZEB1 in prostate cancer 23, TP73 in lung cancer 24, GLI1 in ovarian cancer 25, and JUN in pancreatic cancer." (PMID 31602273, 2019). "Our ChIP data following co-expression of ASXL1 and RUNX1 mutations recognized the deregulation of ID1 in myeloid leukemia cells, suggesting the role of myeloid leukemia transformation by combined mutations were at least partly attributed to the upregulated ID1 expression." (PMID 31640815, 2019). "However, this group proceeded to cross the transgenic Runx1 mouse with the BXH2 mouse model of myeloid leukemia effectively adding an additional copy of Runx1." (PMID 22461792, 2012). "Notably, the leukemic cells from our patients harboring coexisted mutations of ASXL1 and RUNX1 correlated with the upregulation of ID1 gene expression, supporting the role of cooperative mutation of ASXL1 and RUNX1 on ID1 expression and myeloid leukemia transformation." (PMID 31640815, 2019).